SNAI1 (snail family transcriptional repressor 1)
Diseases named in the same sentence as SNAI1 in open-access papers (continued):
Sharing a sentence is not in itself a finding about the gene and the disease.
cancer (continued). "Similarly, our study shows that starvation-induced autophagy leads to the degradation of intracellular SNAI1 and the suppression of cancer progression." (PMID 30736337, 2019). "Our understanding of SNAI1 function is largely defined in neural crest cells, cancers of epithelial origin, and endothelial cells, where it is found to function as a transcriptional repressor that is also a part of chromatin-modifying complexes that regulate cell motility and EMT." (PMID 28614716, 2017). "Hence, it is likely that SNAI1 plays a critical protective role in the circulating immune cells against diseases such as cancer, T2D and RA that are commonly characterized by an inflammatory component." (PMID 28607365, 2017). "MIC2-KD might contribute to ROS decrease and MET also through inhibition of SNAI1, whose expression increases ROS level in cancer cells leading to EMT." (PMID 26689989, 2016). "As shown here, SNAI1 binds several let-7 promoters, and SNAI1 expression is associated temporally with downregulation of let-7 miRs early in reprogramming, consistent with prior evidence that EMT factors suppress let-7 expression in cancer." (PMID 25316190, 2014). "Indeed, several of the 15 synergistic DEGs we validated are directly or indirectly associated with acquisition of stem-like phenotypes in normal or cancer cells, particularly SNAI1, SOX9 and GBX2." (PMID 25401416, 2014). "The SNAI1 gene is a transcription factor that affects the expression of E-cadherin, mainly by promoting the shift to a mesenchymal phenotype, which in turn enhances the invasion and migration of cancer cells through the epithelial–mesenchymal transition (EMT) process." (PMID 40515636, 2025). "SNAI1, a well-established inducer of EMT during embryonic development, is also active in a variety of adult epithelial cells, where it drives the differentiation of mesenchymal stem cells and cancer-associated fibroblasts, fueling tumors with aggressive, metastatic and chemoresistant properties." (PMID 36171192, 2022). "In addition, SNAI1 is considered one of the most prominent suppressors of E-cadherin transcription and plays a key role in the development and progression of various kinds of cancers." (PMID 35223210, 2022). "Interestingly, SNAI1-KO cells presented higher stem cell frequency and underwent a switch in the expression of cancer stemness signaling genes, with significant upregulation of epithelial KIT, ALDH1A1 and SOX2, and analogous downregulation of mesenchymal CD44 and SOX9." (PMID 36171192, 2022). "Finally, SNAI1 is also acetylated by the histone acetyltransferase adenovirus E1A-associated protein (p300) and CREB binding protein (CBP), two key transcriptional coactivators implicated in a multitude of cellular processes including cancer progression." (PMID 34681726, 2021). "Indeed, targeting SNAI1 is a step closer to eradicating cancer." (PMID 34207850, 2021). "The effect of SNAI1 on let-7 levels, and its direct binding to several let-7 family member promoter regions, were detected using ChIP and luciferase assays, providing evidence that SNAI1 binds let-7 promoters and directly represses its expression, leading to an increase in stemness in cancer cells." (PMID 33806868, 2021). "Therefore, the decrease or inactivation of ZNF750 may lead SNAI1 to be free from the expression inhibition and trigger the EMT process associated with increased cancer invasion and metastasis." (PMID 32042337, 2020). "Furthermore, Snai1 has been shown to enhance an immunosuppressive phenotype in cancers." (PMID 30857197, 2019). "Indeed, proteasomes degrade ubiquitinated SNAI1 in cancer cells." (PMID 30736337, 2019). "Thus, the intracellular levels of SNAI1 should be specifically regulated during cancer progression." (PMID 30736337, 2019).
cancer (continued). "Analysis of human cancer datasets confirms that elevated WNT gene expression is associated with high levels of CUX1 and GLIS1 and correlates with genes of the epithelial-to-mesenchymal transition (EMT) signature: VIM, SNAI1 and TWIST1 are elevated whereas CDH1 and OCLN are decreased." (PMID 25217618, 2014). "Some of the confusion over the prevalence of SNAI1 expression in human cancers may also be derived from the use of different antibodies and IHC scoring methods leading to obvious differences particularly with regard to the subcellular compartment considered positive for SNAI1 staining." (PMID 20181105, 2010). "SNAI1, SNAl2 and ZEB1 were overexpressed at mRNA level (16.4-fold, 21.8-fold and 17.2-fold respectively) and protein level in cancer tissue as compared to normal pancreatic tissue." (PMID 41481650, 2026). "The interaction between SNAI1 and ZEB1 is part of a complex network of transcription factors that regulate cell plasticity during cancer progression, and it is commonly observed in various cancers." (PMID 41481650, 2026). "miR-153 has been reported to inhibit the proliferation and invasion of cancer cells through various targets, including Rabl3, ARHGAP18, SNAI1, and Wnt/β-catenin." (PMID 39866238, 2025). "Several studies have highlighted the role of the EMT-TF SNAI1 as an effective inducer of EMT, whilst ZEB and TWIST seem to stabilize the acquisition of the mesenchymal phenotype by cancer cells." (PMID 40332096, 2025). "PELP1 modulates genes that are involved in the epithelial–mesenchymal transition (EMT), including MMPs, SNAIL (SNAI1), TWIST (TWIST1), ZEB (ZEB1), MYC, MTA1, miR-200a, and miR-141, leading to cancer metastasis progression." (PMID 41463382, 2025). "There were no changes in the expression of the transcription factors TWIST, SNAI1 (SNAIL), and SNAI2 (SLUG), master regulatory factors for organogenesis and wound healing tightly involved in the EMT of cancer cells." (PMID 38399969, 2024). "Subsequent experiments further corroborated these findings, affirming the role of SNAI1 in promoting epithelial-mesenchymal transition (EMT) and sustaining cancer stemness." (PMID 39702326, 2024). "The function of SNAI1 in promoting EMT and sustaining cancer stem cell-like properties was validated both in vitro and in vivo." (PMID 39702326, 2024). "Snail family transcriptional repressor 1, SNAI1, is known to be involved in promoting the EMT pathway in human cancer and is a direct downstream target of the HIF-1 pathway as well as the TGF-β signaling pathway." (PMID 39659782, 2024). "Due to their central role in EMT and extensive studies in cancer, ZEB1, ZEB2, SNAI1, SNAI2 and TWIST1 are considered as the core EMT-TFs." (PMID 39164745, 2024). "In cancers, NUP58 regulates the glycogen synthase kinase 3 beta/zinc finger protein Snai1 (GSK-3β/Snail) signaling pathway and bipolar spindle formation, thereby exerting its carcinogenic effect." (PMID 39080077, 2024). "We found a correlation between PROM2 expression and the three EMT markers ZEB1, SNAI1 and TWIST1 in both cancer types." (PMID 38515278, 2024). "The transcription factors regulating EMT, including snail family transcriptional repressor 1 (SNAI1), twist family bhlh transcription factor 1 (Twist1), zinc finger e-box binding homeobox 1 (ZEB1) and ZEB2, regulate cancer migration, invasion, and metastasis." (PMID 39154024, 2024). "A few studies showed the clue that stemness factors SOX2, BMI1, OCT4, or SOX9 can be regulated by ZEB1, SNAI1, or SNAI2, thereby promoting not only stemness and metastasis of cancer cells, but also resistance to radio- and chemotherapy." (PMID 39164745, 2024). "Previous research reported the significant role of HMGA2 in the metastasis of cancer via the regulation of EMT mediated through transcription factors including Slug, SNAI1, as well as Twist20." (PMID 38671227, 2024).
cancer (continued). "Meanwhile, the critical transcription factors, including TWIST1, TWIST2, ZEB1, ZEB2, SNAI1 and SNAI2, participate in the EMT process, leading to cancer cell migration and invasion." (PMID 37794509, 2023). "The findings revealed that normal tissues exhibited higher expression levels of SNAI1, ZEB2, and VIM compared to cancer tissues, and cirrhotic tissues showed higher expression levels than cancerous tissues as well." (PMID 37386390, 2023). "It is interesting, in this regard, that TOX3 downregulation has been reported to facilitate epithelial-to-mesenchymal transition by repression of SNAI1 and SNAI2 in cancer cells." (PMID 36794750, 2023). "The zinc finger protein SNAI1 (also known as Snail; UniProt/Swiss-Prot: O95863, gene name SNAI1), represses the expression of a broad repertoire of epithelial genes, including E-cadherin/CDH1, and is a master regulator of EMT in most cancers." (PMID 36765041, 2023). "ERα inhibits the TGFβ signaling pathway by binding to Smad2 and Smad3 which repress the proliferation of cancer cell; in addition, MTA3 (Metastatic Tumor Antigen 3), a suppressor of Snai1, is upregulated by ERα." (PMID 37444447, 2023). "We therefore evaluated the expression of a panel of epithelial (KRT5, 7, 8, 18, and CDH1), mesenchymal (VIM, FN1, SNAI1, TWIST1, COL1A1, and PRRX1), and cancer stem cell (ALDH1A2, ALDH7A1, CD44, and CCND1) markers in all samples." (PMID 36980717, 2023). "Intercalating agents, such as DOX can affect invasion and proliferation of cancer cells, as well as degradation of extracellular matrix by MMPs (matrix metalloproteinases) through the upregulation of the EMT transcription factor SNAI1." (PMID 38124067, 2023). "A similar effect is observed in Huh7-cells, where cirrhotic hydrogels induced expression of SNAI1 and POU5F1, two important markers for cancer stemness." (PMID 36639512, 2023). "According to previous literature reports, high expression of SNAI1 can promote the invasion ability of cancer cells, low expression of FRMD5 can weaken the metastatic ability of cancer cells, and low expression of FSTL3 also has similar functions." (PMID 36925652, 2023). "Thousands of mRNAs are ELAVL1 targets, including factors fostering diverse cancer traits such as proliferation (cyclins A2, B1, D1, and E1), angiogenesis (HIF1a, PTGS2, and VEGFA), survival (BCL2 and MCL1), and invasion (MMP9 and SNAI1)." (PMID 37298909, 2023). "Relative to SNAI1, regulatory machinery controlling the homeostasis levels of SNAI2 protein under EMT contexts in cancer especially HCC, is less known." (PMID 37596321, 2023). "Recent reports indicate TRERNA1 functions as an eRNA in cancer cells; cDNA overexpression or knockdown of TRERNA1 increases or reduces SNAI1 expression, respectively." (PMID 36923642, 2023). "We used pan-cancer expression data to find 14-LncRNAs that had a high correlation with the EMT markers VIM, CDH1, FN1, SNAI1, and SNAI2." (PMID 36120580, 2022). "Transcript levels of SNAI1 and SNAI2 were increased in most types of tumors when compared with non-cancer tissues." (PMID 35898399, 2022). "Meanwhile, SLC25A13 and its neighboring genes were enriched in transcription factor target genes, including MEF2C, NCOA2, SNAI1, and SOX10 target genes, which were participated in the cancer progression." (PMID 35607442, 2022). "In cancer cell-free EC-adjacent tissues (TA), the expression of MYC, NR5A2, SNAI1, and CXCR2 was higher than in Ctrl samples." (PMID 36140779, 2022). "EMT is the pivotal molecular mechanism involved in cancer metastasis, and E-cadherin is the characteristic marker of EMT; however, other markers, including N-cadherin, MMP-9, and SNAI1 are also important for EMT." (PMID 35300562, 2022). "Our EMT+ subtype exhibit elevated markers VIM, SNAI1, and ZEB1, consistent with our pan-cancer analysis and with known molecular features of epithelial-mesenchymal transition." (PMID 35912202, 2022).
cancer (continued). "Snai1 family transcriptional repressor 1 (SNAI1) is zinc-finger transcription factor and is proved to induce EMT in cancer." (PMID 35912006, 2022). "This corroborates previous findings linking their EMT-TF targets (ZEB1, SNAI1 and SNAI2) with cancer stem cells in CRC." (PMID 35565409, 2022). "Hnf4a expression resulted in a decreased expression of cancer-promoting factors LSD1, SETD1A, PRMT1, FOXM1, FAK, and SNAI1, and also an increased expression of CDH1." (PMID 34595169, 2021). "The genes selected included epithelial (KRT5, CDH1, EpCAM), mensenchymal (VIM, SNAI1, TWIST), stem (ALDH1A1, PROM1), breast specific (ESR1, PALB2) and other genes related to cell cycle or other cancer pathways (CCND1, CTNNB1, Ki67, etc.)." (PMID 34071445, 2021). "CSCs were characterized by the expression of the stem cell markers TWIST, the epithelial cell adhesion molecule (EPCAM), the transcription factors SNAI1 (SNAIL) and SNAI2 (SLUG) and cancer markers such as CD44 and prominin-1 (CD133)." (PMID 34445612, 2021). "On the other hand, nuclear FBXL5 protein also functions as a ubiquitin ligase of SNAI1, which is a key modulator of the EMT and thus involved in multiple kinds of cancers." (PMID 34733841, 2021). "Increased H3K9 acetylation was observed on the promoter of Transforming Growth Factor Beta Receptor 2 (TGFBR2) after the activation of SNAI1/2, leading to transcription of TGF-β, a major player in the regulation of cancer metastasis." (PMID 33803458, 2021). "Transcription factors known to regulate EMT include ZEB1, ZEB2, SNAI1 (SNAIL), SNAI2 (SLUG), and TWIST1 and have been suggested to promote cancer progression, including metastasis." (PMID 34339740, 2021). "LMP2A was reported to induce EMT and increases the number of cancer stem-like cells, which is correlated with the activation of the PI3K/AKT/mTOR pathway and up-regulation of EMT-TF SNAI1." (PMID 34407150, 2021). "SNAI1, known as a canonical transcription suppressor, activates the EMT program and plays a vital role in fibrosis, embryogenesis and cancer progression." (PMID 34718323, 2021). "In CD45-DB samples, downregulation of SNAI1 and upregulation of miR-9 were found in patients with HER2+ tumors, and upregulation of CDH1 in grade 3 cancers, respectively." (PMID 35008529, 2021). "Expression of cancer stemness markers (PROM1 and LGR5), EMT genes (SNAI1, ZEB1 gene and CDH1) and percentage of ALDH + cells were evaluated to assess the effect of sinensetin in modulating cancer stemness and self-renewal." (PMID 33628166, 2020). "The transcription factors, SNAI1, SLUG, ZEB1, and ZEB2, that are involved in EMT, repress E-cadherin to promote the mesenchymal features of cancer cells." (PMID 32218208, 2020). "SNAI1 is considered a marker of EMT, and it is a factor highly involved in the acquisition of resistance to pharmacological treatment in cancer." (PMID 32244885, 2020). "Members of the SNAI family (Snail (SNAI1), Slug (SNAI2), and Smuc (SNAI3)) of transcriptional regulators trigger EMT, and are considered useful indicators of the malignancy of cancer." (PMID 33198344, 2020). "EMT can be induced in a number of ways, including by pleiotropically acting EMT-TFs including SNAI1/2 (Snail1/2), ZEB1/2 and TWIST1/215, these have been shown to have a role in cancer." (PMID 32269211, 2020). "It was reported that overexpression of LOXL2 drove EMT via upregulating the expression of SNAIL (SNAI1/2), ZEB (ZEB1/2) via IRE1-XBP1 signaling pathway or FAK/SRC signaling pathway in cancer cells." (PMID 32211324, 2020). "SNAI1 and ZEB1 are important transcription factors that promote the progress of EMT, and play a key role in the occurrence and development of a variety of cancers." (PMID 33148251, 2020). "Activated Stat3 dimerizes and induces gene expression of a variety of genes, many of which are known to be important for hallmarks of cancers like migration/invasion (Mmp2, Mmp9;) or EMT-like features and immune evasion/suppression (e.g., Snai1;)." (PMID 30857197, 2019).
cancer (continued). "Activation of Akt leads to a significant reduction in E-cadherin expression and to nuclear localization of SNAI1, suggesting a role for the PI3K/Akt signaling pathway in the shift from E-cadherin to N-cadherin expression and in EMT progression in cancer." (PMID 31652503, 2019). "qPCR analyses revealed that the mesenchymal markers (i.e. SNAI1, SNAI2, ZEB1, ZEB2, CDH2, vimentin and fibronectin) expression was decreased in cancer EVs-exposed BRCA1-KO fibroblasts, while the expression of CDH1 was increased." (PMID 31200749, 2019). "E-cad is potentially repressed by Slug (SNAI2) and Snail (SNAI1), which are master regulatory transcription factors involved in the EMT of cancer cells." (PMID 30897151, 2019). "ZEB1, ZEB2, SNAI1, SNAI2 and FOXC2 exhibited consistent positive correlations with the ESTIMATE stromal score in all five cancer types." (PMID 31780722, 2019). "To investigate how the knockdown of the ATG7 gene affects SNAI1 degradation, we transiently transfected plasmids containing ATG7 shRNA and control shRNA into two cancer cell lines (HeLa and H1299) and incubated the cells for 24 h." (PMID 30736337, 2019). "ZEB1, ZEB2, SNAI1, and SNAI2 were significantly and positively correlated with the ESTIMATE immune score in all five cancer types examined." (PMID 31780722, 2019). "To investigate how autophagy-dependent SNAI1 degradation affects the expression of EMT and metastasis-related proteins, we induced autophagy in two different cancer cell lines (H1299 and HeLa) with HBSS for 4 h in the presence or absence of 20 μM chloroquine." (PMID 30736337, 2019). "During the process of dedifferentiation, multiple genes that were demonstrated to be pivotal in cancer stem cell properties were induced, including PDGFRB, NOTCH1, JAG1, HES1, and HEY1 of the Notch signaling, SNAI1 and SNAI217–20." (PMID 29991717, 2018). "POU2F1 induced the transcription of Twist1, Snai1, Snai2 and ZEB1 genes which induce cancer cell EMT." (PMID 28489585, 2017). "Subsequently, p-STAT3 can induce the downstream target genes, such as CCL2, CCL5, ICAM-1, SNAI1, chitinase-3-like 1 (CHI3L1), FBJ murine osteosarcoma viral oncogene homolog (FOS), and Skp2, that promote various cellular processes for cancer progression." (PMID 28157698, 2017). "We highlight cancer-specific down regulation of NRP-1, SNAI1 and SEMA4A in PBMCs with a further decrease of SNAI1, SEMA4A, VEGFR3 and PLXNA1 in patients with advanced disease." (PMID 28607365, 2017). "Here we show that Snail (SNAI1), a key transcriptional repressor of EMT, regulates glucose flux toward PPP, allowing cancer cell survival under metabolic stress." (PMID 28176759, 2017). "Collectively, these findings showed that POU2F1 induced the transcription of Twist1, Snai1, Snai2 and ZEB1 genes which induce cancer cell EMT." (PMID 28489585, 2017). "AKT activation has been demonstrated to increase SNAI1 expression, which promotes EMT and the CSC-like phenotype in cancer." (PMID 26675549, 2016). "We found that FLO-1 expressed significantly higher mRNA levels of the mesenchymal markers SNAI1, ZEB1 and ZEB2 compared to the other cancer cell lines." (PMID 27863424, 2016). "SNAI1, a zinc‐finger transcription factor, plays an important role in the induction of epithelial–mesenchymal transition (EMT) in various cancers." (PMID 27239445, 2016). "To do so, we compared Pol II pausing signal and expression levels on SNAI1, CDH1 and SNAI2 genes in several cancer cell lines grown in steady-state conditions in the absence of activation." (PMID 25820424, 2015). "While the SNAI1 and SNAI2 genes are reported to be frequently reactivated in numerous carcinomas (breast, esophageal, colon, kidney), the status of the related SNAI3 gene has remained unclear." (PMID 24638100, 2014). "Transcriptional factor SNAI1 regulates the epithelial-mesenchymal transition (EMT), a process where cancer cells attain fibroblastic features and thus invade the surrounding structures." (PMID 23894653, 2013).